CRP (C-reactive protein)
Diseases named in the same sentence as CRP in open-access papers (continued):
Sharing a sentence is not in itself a finding about the gene and the disease.
lung cancer (continued). "Further, given the lack of association between hsCRP concentration and the risk of lung adenocarcinoma, it would not be appropriate to use clinical CRP tests to rule out the presence of lung cancer during diagnostic work-up of patients who are symptomatic." (PMID 30606716, 2019). "A double-blind placebo-controlled study of EPA + DHA supplementation in lung cancer patients actively undergoing chemotherapy demonstrated a significant decrease in plasma C-reactive protein (CRP) and interleukin-6 concentrations in the supplemented group after 66 days, relative to controls." (PMID 31569490, 2019). "Therefore, we should validate the activity of IP combined with lung cancer for a developing risk of AE-IP using pretreatment levels of LDH and CRP." (PMID 30808322, 2019). "Furthermore, the albumin, HDL, and CRP levels differed significantly in advanced stage lung cancer patients." (PMID 29941786, 2018). "Interestingly, exploratory data from a randomized trial proposed that IL-1β inhibition results in decreased incidence of Lung cancer in patients with high CRP." (PMID 30365491, 2018). "It isn't clear how CRP is related to lung cancer progression." (PMID 28402963, 2017). "The effect of lung cancer on ln (CRP) remained significant (2.18 vs 1.49) after adjusting for BMI (p = 0.05), age (n.s.), eGFR (n.s.), smoking status at the time of referral (p = 0.02), sex (n.s.), the presence of active malignant disease (p < 0.01), and the presence of heart disease (p = 0.03)." (PMID 28286467, 2017). "Interestingly, several of the pulmonary TB markers have previously been reported as part of a 7-protein classifier for lung cancer, including C9, CRP, and carbonic anhydrase, and C9 and kallistatin were part of a 13-marker signature of mesothelioma." (PMID 28794177, 2017). "SAA and CRP are elevated in the serum of various cancers including lung cancer." (PMID 28121629, 2017). "The “Tex-Mex” pattern was associated with a reduced risk of lung cancer irrespective of the genotype at CRP rs2808630 (P for interaction = 0.27)." (PMID 27230571, 2016). "For CRP at that level, there were 2% of the cohort and 7% of lung cancer cases." (PMID 27805040, 2016). "Clinically, six-week selective inhibition of COX-2, using celecoxib, reduced the severity of cachexia symptoms in lung cancer patients through improving muscle strength and lowering the circulating levels of C-reactive protein (CRP) (marker of systemic inflammation)." (PMID 27642498, 2016). "Moreover, similar to total SAA and CRP, high levels of CRP-SAA were associated with shorter survival in both retrospective and prospective cohorts of lung cancer patients." (PMID 26264146, 2015). "Several studies have suggested that the elevation of serum C-reactive protein (CRP) could be used as a prognostic factor for lung cancer." (PMID 26264146, 2015). "CRP-SAA could be a better prognostic marker for lung cancer than total SAA or CRP, especially in early-stage patients." (PMID 26264146, 2015). "Multivariate Cox analysis showed that CRP-SAA was an independent prognostic marker for lung cancer." (PMID 26264146, 2015). "In an effort to identify possible novel biomarkers to further refine the prognostic prediction accuracy of serum CRP levels for lung cancer, we used differential proteomics technology to identify a specific type of CRP complex in serum samples from lung cancer patients." (PMID 26264146, 2015). "This indicates that CRP measurement may be useful for all lung cancer patients undergoing treatment." (PMID 26425690, 2015). "rs2808630 in CRP and rs2352028 in GPC5 were both associated with lung cancer risk." (PMID 25999661, 2015). "If the serum G-CSF and IL-6 level are measured commonly in lung cancer presenting with elevated white blood cell counts and C-reactive protein level, the more G-CSF and IL-6-producing lung cancer could be found." (PMID 23710188, 2013). "The pooled RR of lung cancer for one unit change in ln CRP was 1.28 (95% CI 1.17–1.41)." (PMID 22912790, 2012).
lung cancer (continued). "This means that elevated CRP levels are a risk predictor for lung cancer, independent of YKL-40 levels." (PMID 22095223, 2012). "Compared to individuals with both low CRP (<1.7 mg l−1) and YKL-40 (<154 μg l−1), individuals with high YKL-40 but low CRP had an HR of gastrointestinal cancer of 3.36 (1.70–6.64), whereas individuals with high CRP but low YKL-40 had an HR of lung cancer of 2.19 (1.24–3.87)." (PMID 22095223, 2012). "One publication was excluded because it investigated the association of CRP with risk of total cancer and there was no outcome of lung cancer." (PMID 22912790, 2012). "We also found that CRP was significantly associated with increased risk of lung cancer among men (RR 1.18, 95% CI 1.09–1.28) but not among women." (PMID 22912790, 2012). "The 10 studies on CRP involved a total of 1918 lung cancer cases." (PMID 22912790, 2012). "A recent 10-year population-based observational cohort study reported that baseline serum C-reactive protein was significantly associated with lung cancer, independent of smoking." (PMID 18433475, 2008). "The biological basis for the association of acute-phase proteins, including CRP, SAA, and AAT, with lung cancer remains largely unknown." (PMID 16117833, 2005). "Serum C-reactive protein levels and plasma fibrinogen levels were significantly higher and serum albumin concentration was significantly lower in lung cancer patients with detectable serum IL-6 levels than in those without detectable serum IL-6 levels and in patients with benign lung diseases." (PMID 7734307, 1995). "In conclusion, CRP cutoff values were determined in the present study with the aim of predicting an infection that might delay chemotherapy in patients with a diagnosis of lung cancer receiving chemotherapy." (PMID 40125102, 2025). "However, multivariate analysis revealed that albumin, rather than CRP, was more strongly associated with length of hospital stay in older male patients with lung cancer undergoing chemotherapy." (PMID 40786260, 2025). "Moreover, chronic inflammation, a known seventh hallmark of cancer development, substantiated by epidemiological research, demonstrated positive correlations between inflammatory markers, such as CRP, and various cancers, including breast, colorectal, and lung cancers." (PMID 40282466, 2025). "Higher age, fast-growing metastases (from bladder cancer, colorectal, hepatocellular, lung cancer, malignant melanoma, unknown origin), pathologic fracture or >1 metastasis and elevated CRP predict shorter patient survival and may represent a relative contraindication in this regard." (PMID 40105218, 2025). "Although the etiological role of CRP in lung cancer has not been confirmed, circulating CRP may serve as an early diagnostic marker for lung cancer in current smokers." (PMID 39687887, 2024). "Furthermore, CRP was found to act as a central factor connecting other cytokines and adipokines that contributed to lung cancer progression, suggesting that it might act as a bridge linking these aspects." (PMID 37929799, 2023). "Moreover, regulatory network analysis indicated that CRP might be a central factor in modulating sequential cascades, thereby contributing to lung cancer progression." (PMID 37929799, 2023). "Additionally, the prognosis of patients with lung cancer and elevated CRP level is poorer." (PMID 37373957, 2023). "However, few observational studies have shown that CRP affects lung cancer progression." (PMID 37929799, 2023). "Our research showed that CPFE with lung cancer was more common in elderly men and smokers, mainly in heavy smokers, with a more severe systemic inflammatory response represented by significantly elevated CRP, IL-6 and fibrinogen, which is in line with the results of previous studies." (PMID 36769748, 2023).
lung cancer (continued). "C-reactive protein (CRP) and albumin can represent the inflammatory response and nutritional status in a better way, and studies have confirmed that high CRP and low albumin levels are significantly correlated with the poor prognosis of patients with lung cancer." (PMID 36684183, 2022). "The pro-CRP, CEA, and NSE could be used as diagnostic indicators for malignant lung tumors." (PMID 35572829, 2022). "Thus, additional studies are needed to verify whether the relationship between CRP levels and survival among lung cancer patients vary with the histologic subtypes." (PMID 31148582, 2019). "In conclusion, this large cohort study suggested that subjects with high urinary nitrite/nitrate concentrations had an increased risk of lung cancer and this association was independent of smoking, CRP, 8-isoprostane levels, and other established lung cancer risk factors." (PMID 31565153, 2019). "Other established prognostic factors for lung cancer include performance status (Karnofsky or ECOG (Eastern Cooperative Oncology Group) classification), weight loss (e.g., > 5%) and systemic inflammation (C-reactive protein or modified Glasgow Prognostic Score)." (PMID 30173391, 2019). "If ln (CRP) were only a surrogate marker of FEV1 loss, the second adjustment of ln (CRP) would be expected to equalize the difference in ln (CRP) between patients with lung cancer and patients with other cancers, but this hypothesis was not confirmed." (PMID 28286467, 2017). "Moreover, univariate and multivariate Cox analyses also showed that only CRP-SAA could be used as an independent prognostic marker for early-stage lung cancer patients." (PMID 26264146, 2015). "The performance of CRP-SAA in lung cancer prognosis may be related to its biological functions." (PMID 26264146, 2015). "Therefore, CRP-SAA levels could be considered a more sensitive and relevant indicator of early lung cancer progression than CRP or SAA alone." (PMID 26264146, 2015). "We evaluated whether CRP-SAA could be a prognostic marker for lung cancer." (PMID 26264146, 2015). "Next, we investigated whether CRP-SAA or total SAA in serum could be used as a lung cancer marker." (PMID 26264146, 2015). "In this retrospective analysis, we evaluated the prognostic value of routine hematological markers (Hb, CRP, fibrinogen, D-dimer) integrated with ECOG performance status in patients with lung cancer." (PMID 41226999, 2025). "On the other hand, CRP, albumin, total cholesterol, and cancer staging are factors that impact the occurrence of CRA in lung cancer patients with normal serum iron." (PMID 38562035, 2024). "These biomarkers, including CYFRA 21-1, NSE, ProGRP, SCC, CEA, tumor M2-PK, CRP, LDH, tumor-suppressor genes, and oncogenes, CA125, CgA, NCAM, and TPA, are useful in the diagnosis and clinical management of lung cancer." (PMID 39195131, 2024). "We recognize that the individual components of the NUn score—CRP, ALB, and WBC count—have been previously studied in the context of lung cancer prognosis." (PMID 39513125, 2024). "CRA in lung cancer is mainly related to surgery, chemotherapy, Karnofsky Performance Status (KPS) score, serum iron, C‐reactive protein (CRP), albumin, and total cholesterol (p < 0.05)." (PMID 38562035, 2024). "In summary, chemotherapy, KPS score, serum iron, CRP, albumin, and total cholesterol are all factors related to CRA in lung cancer patients." (PMID 38562035, 2024). "Univariate analysis revealed statistically significant differences in the impact of age, gender, cancer staging, surgery, radiation therapy, CRP, albumin, and total cholesterol on the incidence of CRA in lung cancer patients with normal serum iron levels." (PMID 38562035, 2024). "This study focuses on evaluating serum parathyroid hormone (PTH), C-reactive protein (CRP), lipid profile parameters, and interleukin-6 (IL-6) in relation to the stages of lung cancer, exploring their potential as biomarkers for assessing disease severity." (PMID 39816276, 2024).
lung cancer (continued). "In addition, a systemic analysis showed that high CRP expression could predict prognosis and correlate with higher mortality in lung cancer and other solid tumors, and another study found that lung cancer survival was proportionally decreased with higher serum CRP levels." (PMID 37929799, 2023). "Furthermore, recent reports have shown that a CRP flare response, defined as a transient increase in serum CRP levels after ICI initiation followed by a subsequent decrease below baseline, is associated with better prognosis in renal cell carcinoma, urothelial carcinoma, and lung cancer." (PMID 39516365, 2023). "Lung cancer patients display elevated plasma levels of soluble TNF receptor 1 (sTNF-R1), fibrinogen, and C-reactive protein (CRP), as well as reduced albumin, highlighting sustained pro-inflammatory conditions." (PMID 36158184, 2022). "Patients with benign lung tumors were taken as controls; the blood immune biochemical indicators progastrin-releasing peptide (pro-CRP), carcinoembryonic antigen (CEA), and neuron-specific enolase (NSE) in patients with malignant lung tumors were analyzed." (PMID 35572829, 2022). "Chronic inflammation has been shown to be a major player in lung cancer, and a number of studies have been carried out to correlate inflammatory biomarkers such as C-reactive protein (CRP), with the subsequent development of lung cancer." (PMID 36532545, 2022). "After comparison, it was found that serum levels of pro-CRP, NSE, and CAE of patients with malignant lung tumors were significantly higher than those of patients with benign lung tumors (P < 0.05)." (PMID 35572829, 2022). "The positive mode has marker traits pulmonary function and the C-reactive protein, and the few markers genes (IL6R, ARHGAP10, BCL7B, PABPC4) are also involved in immune response and lung cancer progression." (PMID 34157017, 2021). "The C-reactive protein (CRP)/albumin (Alb) ratio (CAR) has been identified as a novel inflammation-based prognostic marker in several cancers, including esophageal cancer, lung cancer, hypopharyngeal and laryngeal cancer, and nasopharyngeal cancer." (PMID 33686103, 2021). "A study suggested that a panel of four biomarkers composed of prolactin, CRP, NY-ESO-1, and HGF to screen for lung cancer." (PMID 31976313, 2020). "The data indicate that only CRP and SAA are correlated in controls, while there are two subsets of correlated proteins in both lung cancer groups." (PMID 28121629, 2017). "In this multivariate survival analysis on patients with lung cancer, low NLR and low CRP (compared to both high) was shown to predict better overall survival (RR: 0.403 95% CI 0.240–0.689 p = 0.0012)." (PMID 29196718, 2017). "The use of serum markers, namely LDH (lactate dehydrogenase), CRP (C-reactive protein), CEACAM, NSE, and CYFRA 21-1, has enhanced accuracy of lung cancer diagnosis to 94.8%." (PMID 29137182, 2017). "Therefore, CRP-bound complexes in the serum may be potential prognostic biomarkers of lung cancer." (PMID 26264146, 2015). "The prognostic value of CRP-SAA is higher than that of CRP and SAA individually, especially for early-stage lung cancer patients." (PMID 26264146, 2015). "The serum levels of CRP-SAA and total SAA were evaluated in samples from two independent cohorts of lung cancer patients and healthy control samples using the two ELISA systems." (PMID 26264146, 2015). "In our study, we first found that CRP bound to SAA and formed complexes in the serum of lung cancer patients." (PMID 26264146, 2015). "In the current study, where all cohorts were matched for smoking exposure, the CC genotype (low CRP level) was less frequent in both COPD and lung cancer cases although only achieved significance in the lung cancer only sub-phenotype." (PMID 21304900, 2011). "We found increased levels of CRP, SAA, α-1-antitrypsin (AAT) by two distinct antibodies, and MUC1, and decreased levels of transferrin and gelsolin, in lung cancer sera." (PMID 16117833, 2005).
lung cancer (continued). "The pattern of increased abundances of CRP, SAA, AAT and MUC1 in lung cancer patient sera that were observed in our microarray-based study is concordant with previous studies of individual proteins." (PMID 16117833, 2005). "The significant increases in CRP and SAA protein levels found in the serum of lung cancer patients by protein microarray were confirmed by immunoassay." (PMID 16117833, 2005). "Because of the heterogeneous nature of the population in terms of disease site, the correlation between CRP and 1/TMAX was also examined in the sub-groups of breast and lung cancer patients." (PMID 12177794, 2002). "The present study aimed to evaluate the prognostic significance of four routinely measured hematological parameters—Hb, CRP, fibrinogen and D-dimer—together with ECOG performance status in patients with lung cancer treated at a regional oncology center in Eastern Europe." (PMID 41226999, 2025). "Similar findings were observed with patients with lung cancer (n = 13) supplemented with 510 mg of EPA+ 340 mg DHA for 9 wk, which resulted in lower plasma concentrations of IL-6 and CRP (P < 0.05 for both) after 9 wk of treatment, compared with the placebo group (850 mg olive oil)." (PMID 40523478, 2025). "The objective nutritional indices, such as C-reactive protein-to-albumin ratio (CAR), advanced lung cancer inflammation index (ALI), prognostic nutritional index (PNI), geriatric nutritional risk index (GNRI), and controlling nutritional status (CONUT) score, were calculated." (PMID 41586234, 2025). "C-reactive protein was not correlated with either NLR (p-value: 0.0669) or PLR (p-value: 0.6733) in lung cancer patients." (PMID 39199673, 2024). "Cytokine and adipokine arrays combined with a comprehensive analysis using meta-database software indicated upregulation of C-reactive protein (CRP) in the LC-HFD group, which presented with increased lung cancer proliferation and metastasis; this was confirmed experimentally." (PMID 37929799, 2023). "A study tested a biomarker panel composed of Cyfra 21.1, CEA, CA125, and CRP in 63 patients with lung cancer and 87 noncancer patients." (PMID 37958411, 2023). "The different roles played by each CRP isoform at sites of local inflammation and infection, but what is certain is that CRP is an immune regulator, not just a marker of inflammation or infection, activating C1q to promote lung cancer progression." (PMID 37036321, 2023). "CRP in patients with ICIaP was significantly higher compared to patients with lung cancer (p = 0.001) but not to healthy controls or patients with ILD other than ICIaP (p = 0.291 and p = 0.057, respectively)." (PMID 34347128, 2022). "Besides, the blood immune biochemical indicators of pro-CRP, CEA, and NSE were significantly higher in malignant lung tumor patients." (PMID 35572829, 2022). "In addition, the assessment of blood circulating proteins like CEA, CYFRA 21-1 (serum cytokeratin 19 fragment), fibrinogen, C-reactive protein (CRP), and neuron-specific enolase (NSE), as markers of lung cancer progression, has been considered inconclusive." (PMID 36213817, 2022). "The results demonstrated that all the levels of pro-CRP, CEA, and NSE in malignant lung tumor patients increased significantly, which suggested that these indicators can be used as biochemical indicators for the diagnosis of malignant lung tumors." (PMID 35572829, 2022). "It was observed that the pro-CRP, NSE, and CAE in the serum of patients with malignant lung tumors were 175.6 pg/mL, 33.6 ng/mL, and 31.9 ng/mL, respectively, while those of patients with benign lung tumors were 28.9 pg/mL, 12.5 ng/mL, and 10.8 ng/mL, respectively." (PMID 35572829, 2022). "Additionally, considering that inflammatory markers can predict cancer progression, PCT and CRP levels and NLR in patients with TF were compared by lung cancer stages." (PMID 32908505, 2020).